KIF2C (kinesin family member 2C)
Diseases named in the same sentence as KIF2C in open-access papers (continued):
Sharing a sentence is not in itself a finding about the gene and the disease.
cancer (continued). "This study indicated that KIF2C is a novel prognostic biomarker that determines cancer progression and also a target for the therapy of EC and correlated with tumor immune cells infiltration in EC." (PMID 34650608, 2021). "In the present study, we used The Cancer Genome Atlas (TCGA) project and Gene Expression Omnibus databases to conduct a pan-cancer analysis of KIF2C for the first time, including gene expression, survival status, and genetic alteration." (PMID 35153749, 2021). "We then divided the cancer samples into groups based on high or low expression levels of KIF2C, and assessed overall patient outcomes within these two groups." (PMID 34663310, 2021). "In this study, we performed a series of bioinformatics analyses to identify KIF2C gene features in pan-cancer." (PMID 35153749, 2021). "Our findings here suggest that KIF2C is a novel prognostic biomarker that determines cancer progression and also as a target for the therapy of EC, which correlated with tumor immune cells infiltration in EC." (PMID 34650608, 2021). "Consistent with our results, previous studies have reported the overexpression of KIF2C in several cancer types." (PMID 32748349, 2021). "It is generally accepted that KIF2C has been reported to be upregulated in several cancers and promoted tumor proliferation and progression." (PMID 34650608, 2021). "Analysis of the data in The Cancer Genome Atlas (TCGA) database indicated that KIF2C expression was increased in almost all cancer types, including HCC." (PMID 32748349, 2021). "Results from integrated analyses show that KIF2C is overexpressed in several solid cancers and has already been identified as an important prognostic factor for cancers." (PMID 33187219, 2020). "For example, we conducted a retrospective study of patients treated at a single cancer center and just analyzed KIF-2C expression using immunohistochemistry." (PMID 27563815, 2016). "KIF2C expression may enhance mTORC1 signaling transmission, which in turn may facilitate the growth, invasion, and motility of cells in cancer." (PMID 39911278, 2025). "Although much remains to be explored regarding KIF2C's specific role in OS, its known involvement in critical cancer‐related pathways and tumor metastasis suggests that KIF2C may contribute similarly to OS progression." (PMID 40292920, 2025). "Furthermore, some Kinesin family members, like KIF2C, KIF20A, KIF18A, and KIF15, have been linked to cancer progression and potentially to resistance against hormone-based therapies." (PMID 40869915, 2025). "Notably, the mRNA and protein levels of KIF2C are upregulated in many cancer types, and its mRNA levels correlate with the prognosis of patients with multiple cancer types, demonstrating its oncogene properties." (PMID 41333555, 2025). "Additionally, the enrichment of each pathway varied across different cancers, reflecting the regulatory and functional mechanisms of KIF2C in the context of tumor type‐specific backgrounds." (PMID 40292920, 2025). "Additionally, KIF2C is involved in key signaling pathways, such as the Wnt/β‐catenin and mTORC1 pathways, which are crucial for cancer cell proliferation, invasion, and metastasis." (PMID 40292920, 2025). "Conversely, inhibition of KIF2C has been shown to suppress tumor cell proliferation, suggesting that it may serve as a potential therapeutic target in cancer treatments." (PMID 40433108, 2025). "Nevertheless, we still maintain that KIF2C may exert oncogenic effects through analogous mechanisms across multiple cancer types, which endows it with potential as a pan-cancer therapeutic target." (PMID 41333555, 2025). "Overall, these data strengthen the crucial role of KIF2C in progression of PCa and suggest an involvement in regulating the expression of important immunomodulatory cytokines as well as fueling the malignancy of the cancer cells." (PMID 38344808, 2024).
cancer (continued). "Notably, we identified different proteins that were previously associated with the adaptation to CIN in cancer, including the kinesin-like protein KIF2C/MCAK and the master SAC regulator MPS1/TTK." (PMID 38177531, 2024). "Indeed, an increasing number of publications indicate that KIF2C is aberrantly expressed in multiple cancer entities." (PMID 38344808, 2024). "Moreover, clinical trials including KIF2C expression data or the use of highlighted gene signatures for the design of treatment schedules for multiple cancer entities would largely expand the significance of KIF2C’s role in the outcome of patients." (PMID 38344808, 2024). "KIF2C was shown to be involved in multiple crucial cellular processes including cell migration and invasion, DNA repair, senescence induction and immune modulation, which are all known to be critical during the development of malignant tumors." (PMID 38344808, 2024). "Finally, it will be of great interest, if KIF2C is indeed able to modulate the immune response in the TME as suggested in some cancer entities and how this is facilitated by a protein mainly known for its MT destabilizing function." (PMID 38344808, 2024). "This might help to establish KIF2C as a biomarker for the diagnosis or evaluation of at least three cancer entities." (PMID 38344808, 2024). "We demonstrated that targeting cells with supernumerary centrosomes and elevated Nek2A/KIF2C expression could selectively kill cancer cells, a finding substantiated both in vitro and in vivo." (PMID 38493150, 2024). "Overall, these reports indicate KIF2C’s involvement in cell migration and invasion of cancer cells." (PMID 38344808, 2024). "As a consequence, KIF2C is regarded as a potential cancer therapy target." (PMID 38344808, 2024). "Additionally, a recent study showed that inhibitors against KIF2C’s depolymerization activity were sufficient to induce aneuploidy in different cancer cell lines, highlighting KIF2Cs, function in safe-guarding chromosome stability during mitosis." (PMID 38344808, 2024). "This, in addition to its MT destabilizing function, may explain how KIF2C is involved in resisting cell death induced by known anti-cancer drugs, such as taxanes and doxorubicin, that are known to cause DNA damage." (PMID 38344808, 2024). "KIF2C, a member of the kinesin-13 family known for regulating microtubule dynamics, has not been extensively studied in the context of centrosome clustering in human cancer." (PMID 38493150, 2024). "Consistent with previous studies, our GSEA data also suggested that KIF2C is involved in the regulation of DNA replication and cell cycle control, which might be also responsible for its role in cancer development." (PMID 37016301, 2023). "We posit that this could be due to elevated cGAMP production along the oncogenic trajectory, as we showed that CIN-high pro-metastatic Kif2c+ cancer cells expressed higher levels of Cgas." (PMID 38117852, 2023). "Overexpression of KIF2C could promote cancer cell proliferation, migration, invasion, and metastasis by increasing the mTORC1 signaling transduction." (PMID 37016301, 2023). "Not only that, but we observed that KIF2C overexpression promoted tumor metastasis in a mouse lung tumor formation assay by tail vein injection, resulting in large areas of metastasis and the diffusion of cancer cells in the lungs of the mice." (PMID 36900292, 2023). "Notably, Cgas expression is the highest in a distinct cancer cell cluster annotated for overexpressing Kif2c, which has been reported to drive CIN and metastasis." (PMID 38117852, 2023). "Together with results from other studies, our data suggest that the function of KIF2C in immune cells infiltration may be cancer type-specific." (PMID 37016301, 2023). "It has been hypothesized that KIF2C silencing synergizes and enhances the effects of paclitaxel on cancer cells by interfering with spindle separation, which prolongs mitotic time, resulting in mitosis and apoptotic disorders." (PMID 37717078, 2023).
cancer (continued). "KIF2C expression was higher among patients classified as N0 and N1 based on cancer stage." (PMID 35720323, 2022). "According to the data from CCLE, KIF2C was highly expressed in different cancer cells." (PMID 35720323, 2022). "In addition, we also investigated the correlation of KIF2C with PFI, DFI and DSS, and the results showed that KIF2C was significantly associated with poor prognosis in several cancer types." (PMID 35685442, 2022). "However, the mechanism of KIF2C in pan-cancer is unclear.Data were obtained from public databases, including The Cancer Genome Atlas (TCGA), UALCAN, TIMER and CellMiner." (PMID 35685442, 2022). "Overexpression of KIF2C increased DOX resistance in cancer cells." (PMID 34663310, 2021). "In this study, we comprehensively analyzed the characteristics of KIF2C in various cancers." (PMID 35153749, 2021). "KIF2C elevated levels were observed in some types of cancer." (PMID 34663310, 2021). "We found that KIF2C was highly expressed and corresponded to a poor prognosis in various cancers." (PMID 35153749, 2021). "Previous studies have reported that KIF2C is overexpressed in a variety of cancer types." (PMID 35153749, 2021). "In the TIMER database, we investigated the expression of KIF2C in pan-cancer." (PMID 35153749, 2021). "We found that KIF2C was frequently abnormally expressed in various types of cancer." (PMID 35153749, 2021). "Moreover, the knockdown of KIF2C inhibited the expression of Ki-67 and the growth of tumors in the nude mouse xenograft cancer model." (PMID 34650608, 2021). "This suggested that the expression of KIF2C may be related to the active proliferation of cancer cells." (PMID 35153749, 2021). "Kinesin family member 2C (KIF2C) has been reported as an oncogene in cancers." (PMID 34650608, 2021). "Therefore, the deregulation of KIF-2C expression likely plays a role in cancer development and progression." (PMID 27563815, 2016). "Many germ cell proteins, including KIF-2C, are aberrantly expressed in cancer." (PMID 27563815, 2016). "We found seven upregulated genes (MCM10, RAD51-associated protein 1 (RAD51AP1), KIF2C, Y_RNA, FAM64A, CDC6, and CDCA8) and six downregulated genes (ADAMTS8, ATP1A2, MYH1, OGN, OMD, and ZBTB16) in at least two phenotypes containing either ALT high/middle or TEL high/middle regardless the cancer type." (PMID 38763334, 2024). "Furthermore, the advances in conditional knockout mice confer the possibility to study KIF2C’s role during malignant tumor as well as organ formation and development, as shown recently for the nervous system in conditional knockout KIF2Cflox/flox/NestinCre mice." (PMID 38344808, 2024). "Moreover, overexpression of KIF2C could promote cancer cell proliferation, migration, invasion, and metastasis by increasing the mTORC1 and MEK/ERK signaling transduction and modulating MT dynamics and focal adhesion turnover." (PMID 37016301, 2023). "Furthermore, in a transformed model, knocking down K-Ras or inhibiting ERK1/2 activation lowered KIF2C expression, suggesting that KIF2C might be a potential target for cancer medication treatment." (PMID 35720323, 2022). "KIF2C expression was significantly correlated with TMB, MSI, MMRs, and immune checkpoint genes, and with the level of immune cell infiltration such as tumor-associated macrophage (TAM), cancer-associated fibroblasts (CAFs), myeloid-derived suppressor cells (MDSCs) and Tregs." (PMID 35685442, 2022). "Thus, the difference in KIF2C expression in various cancers suggested that it might have different biological functions in different types of cancers." (PMID 35153749, 2021). "Therefore, KIF-2C may have antigenicity and the capacity to elicit strictly cancer-specific immune responses." (PMID 27563815, 2016). "Collectively, these findings support a tumor-promoting role of KIF2C in LUAD, likely through enhancing proliferative and invasive properties of cancer cells." (PMID 41341805, 2025).
cancer (continued). "The GSEA results showed that the G2M_CHECKPOINT and E2F_TARGETS pathways were highly expressed in all cancers except for STAD, which aligns with the biological role of KIF2C." (PMID 40292920, 2025). "Top presented HLA class I TAP-U source genes KIF2C, MAGED4, and EGFR have shown immunogenicity in cancer context." (PMID 39136024, 2024). "Genes related to cancer stem cells and tumorigenesis, such as KPNA2, ECT2, ERCC6L and TUBB4B, and the cell-cycle regulators DLGAP5, KIF2C and BUB3 were also significantly upregulated in the CSPG+ group, and clustered well within the same area." (PMID 38251863, 2024). "Co-expression network analysis showed that CDCA3, GSG2, KIF2C, NCAPH and PLK1 were positively correlated with ORC1 in cancer, and the functional enrichment mainly included cytosol, ATP binding and cell division." (PMID 37833711, 2023). "Co-expression network analysis showed that CDCA3, GSG2, KIF2C, NCAPH and PLK1 were positively correlated with ORC1 in cancer, and enrichment analysis showed a correlation with cytosol, ATP binding and cell division." (PMID 37833711, 2023). "Several publications have reported the relationships between these five ER-related genes (SPP1, KIF2C, LPCAT1, KPNA2, and FMO3) and cancers." (PMID 35915607, 2022). "Myeloid-derived suppressor cells (MDSCs) have immunosuppressive characteristics, and we analyzed the correlation between KIF2C and MDSCs in pan-cancer by TIMER 2.0 and found that KIF2C was significantly positively correlated with MDSCs in most tumors." (PMID 35685442, 2022). "However, it is unknown if PKM2 and KIF2C may interact to affect the cancer development." (PMID 34663310, 2021). "Analysis from CHAT revealed that BIRC5, E2F2, KIF2C, FOXM1, and MCM5 were mainly involved in sustaining proliferative signaling in cancer development, with npmi values of 0.15, 0.222, 0.168, 0.218, and 0.157, respectively." (PMID 31579605, 2019). "KIF2C and KIF20A were reported, in a study based on ChIP-chip assays, as the target of E2F family including E2F1, E2F4, and E2F6 in normal and cancer cells of breast tissue." (PMID 30813560, 2019). "Markedly, the CTA genes ATAD2, CEP55, FANCA, KIF2C, NUF2, OIP5, and PBK had significantly positive expression correlations with the PLK1 expression in 30 cancer types (Pearson correlation, FDR<0.1)." (PMID 30631355, 2018). "To investigate whether KIF2C exerts specific oncogenic effects in HCC, we systematically evaluated the expression patterns of KIF2C in pan-cancer cohorts." (PMID 41333555, 2025). "In addition, it is of importance to investigate whether the increase of KIF2C with its oncogenic potential is a driving factor in carcinogenesis because of its role in chromosome instability, or whether it is a pathological consequence of the unrestricted cell cycle of cancer cells." (PMID 38344808, 2024). "Currently, the function of KIF2C in tumors is not clear, and a comprehensive pan-cancer analysis is needed." (PMID 35685442, 2022). "The protein immunohistochemical staining indicated the levels of CDC20 and KIF2C were nearly the same in normal and cancer tissues, which was inconsistent with the result that the expression levels of CDC20 and KIF2C in tumor tissues were higher than normal tissues." (PMID 35456460, 2022). "We found that the mRNA levels of KIF2C were significantly correlated with methylation in different cancer types, and there was a correlation between DNMT and KIF2C expression, suggesting that DNA methylation may also be involved in the regulation of KIF2C." (PMID 35685442, 2022). "For example, cancer cells adapt to decreased microtubule-kinetochore dynamics and suppressed CIN induced by treatment with KIF2C/MCAK inhibitors by adjusting AURKB levels, ultimately returning the cancer cells to their original level microtubule-kinetochore dynamics and chromosome mis-segregation." (PMID 33066048, 2020).
cancer (continued). "Of note, 6 CTA genes CEP55, KIF2C, TTK, OIP5, CASC5, and NUF2 had higher expression levels in the higher-TMB subtype of at least 15 cancer types, while had higher expression levels in the lower-TMB subtype of at most 3 cancer types." (PMID 30634925, 2019). "KIF-2C expression was observed in the cytoplasm of cancer cells, but not in the non-cancerous cells." (PMID 27563815, 2016). "Not surprisingly, up-regulations of KIF2C have been documented in multiple human cancers and KIF2C has been suggested to play an important role in carcinogenesis." (PMID 25411964, 2014). "Furthermore, the mitotic effect of MCAK/Kif2C OE has not been studied despite the fact that the protein is overexpressed in many cancers and has the potential to increase chromosome instability to promote tumor evolution." (PMID 40027728, 2025). "Moreover, the expression of KIF2C was significantly associated with infiltrated immune cells such as B cell, CD8+ T cell, CD4+ T cell, myeloid-derived suppressor cells, Tregs cells and non-immune cells including cancer-associated fibroblasts." (PMID 38344808, 2024).